FASN (fatty acid synthase)
Diseases named in the same sentence as FASN in open-access papers (continued):
Sharing a sentence is not in itself a finding about the gene and the disease.
T-cell lymphoma (1 paper, 2023). "The elevated level of FASN correlates with a low level of apoptosis in transplantable murine T-cell lymphoma." (PMID 37256177, 2023). "Augmented differentiation and antitumor activation of macrophages indicate decreased immunosuppression in the tumor-bearing host of a T-cell lymphoma treated with a FASN inhibitor." (PMID 37256177, 2023). "With a murine model of T-cell lymphoma, FASN has been demonstrated to be a targetable enzyme that weakens the chemoresistant amplitude." (PMID 37256177, 2023). "Pharmacological inhibition of FASN through orlistat modulated the tumor microenvironment and reversed the drug resistance in a murine T-cell lymphoma." (PMID 37256177, 2023). "Upregulation of FASN in extra-nodal nasal NK/T-cell lymphoma cells was found to correlate with their survival adaptation." (PMID 37256177, 2023). "In a murine transplantable T-cell lymphoma, pharmacological inhibition of FASN has a direct inhibitory effect on the survival of tumor cells." (PMID 37256177, 2023). "One of the plant compounds, methyl jasmonate, decreases the levels of SREBP as well as FASN expression in cells of T-cell lymphoma." (PMID 37256177, 2023). "SREBP favors the elevated expression of FASN in T-cell lymphoma." (PMID 37256177, 2023).
tongue squamous cell carcinoma (1 paper, 2018). A squamous cell carcinoma that arises from the tongue. "The specific inhibitor of FASN was able to reduce the proliferation of OSCC cells and metastasis of orthotopic tongue squamous cell carcinomas." (PMID 30233549, 2018).
type 1 diabetes (1 paper, 2014). "We further investigated whether type 1 diabetes affected the transcription of genes involved in lipid metabolism such as fatty acid synthase (FASN), lipoprotein lipase (LPL) and hormone-sensitive lipase (HSL) in each depot." (PMID 25170835, 2014).
urinary tract tumors (1 paper, 2025). "For example, in lipid metabolism, studies have shown that MLYCD, FASN, ACSM, and ACSL play important roles in the progression of urinary tract tumors." (PMID 41281744, 2025).
vitamin D deficiency (1 paper, 2025). A nutritional condition produced by a deficiency of VITAMIN D in the diet, insufficient production of vitamin D in the skin, inadequate absorption of vitamin D from the diet, or abnormal conversion of vitamin D to its bioactive metabolites. "Additionally, vitamin D deficiency elevates fatty acid synthase levels, reduces leptin concentrations, inhibits lipolysis, and facilitates lipid accumulation." (PMID 40521355, 2025).
cancer (980 papers, 2006 to 2026). A tumor composed of atypical neoplastic, often pleomorphic cells that invade other tissues. "By producing fatty acids, FASN is implicated in numerous crucial cellular processes, but it is also frequently overexpressed in cancer." (PMID 41550490, 2026). "FASN has been linked to the advancement of various cancers, including hepatocellular carcinoma, rectal carcinoma and breast cancer." (PMID 40764609, 2025). "Overexpression or hyperactivation of FASN is closely linked to the progression and prognosis of several cancers and diseases." (PMID 41345744, 2025). "Increased de novo lipogenesis, promoted by the Warburg effect, is a recurrent cancer hallmark with FASN as the pivotal enzyme involved in deregulating this metabolism." (PMID 40684943, 2025). "Upregulation of FASN promotes cancer progression and is associated with poor prognosis in patients with multiple tumors." (PMID 40890129, 2025). "FASN (fatty acid synthase), a central enzyme in lipid metabolism, is frequently overexpressed in cancer cells, where it is linked to rapid proliferation and tumor progression." (PMID 40703521, 2025). "The key enzyme involved in FA synthesis, FASN, is associated with a higher risk of cancer recurrence and mortality." (PMID 39402211, 2025). "Overexpression of FASN has been observed in various cancers, including NSCLC, and is associated with poor prognosis and aggressive tumor behavior." (PMID 40469185, 2025). "The differential expression and activity of FASN between malignant and normal cells underline its potential as a molecular target for anti-cancer drug development." (PMID 40733158, 2025). "Elevated expression and activity of FASN contributes to the survival of cancer cells and has implicated in the progression of ESCC." (PMID 39925801, 2025). "Overexpression of FASN is linked to tumor progression and poor prognosis in several cancers, including triple-negative breast cancer, where it is upregulated in 70% of newly diagnosed cases." (PMID 40723225, 2025). "FASN-related lipogenic phenotype is related to malignancy, stemness, and therapy resistance and is also a hallmark of invasive cancers." (PMID 40133683, 2025). "The expression level of FASN also increases in the early stages of cancer and is associated with poor prognosis, indicating that targeting FASN can be a crucial therapeutic option for aggressive GB cells by providing a selective advantage." (PMID 40133683, 2025). "Upregulation of FASN has been observed in multiple cancers, including BLCA, and is associated with poor prognosis." (PMID 41153362, 2025). "EGFR inhibitors have been widely used to overcome EGFR-TKI resistance, while FASN, a key factor in cancer cell survival, has been linked to poor prognosis, recurrence risk, and drug resistance." (PMID 40872626, 2025). "The increase in FASN expression and activity is observed in the early stages of tumorigenesis and is associated with cancer progression." (PMID 41421797, 2025). "FASN is crucial in fatty acid biosynthesis and has been associated with the tumorigenesis and progression of various cancers, including ccRCC." (PMID 40533456, 2025). "Increased FASN expression has been linked to BC progression as well as the development of resistance to anti-cancer therapeutics." (PMID 40548063, 2025). "FASN is known to facilitate nucleic acid, protein, and lipid synthesis to support cancer cell metabolism and is implicated in various cellular functions such as immune evasion and resistance to cell death." (PMID 39567194, 2025). "FASN activation is an early and nearly universal hallmark of most human cancers or their precursor lesions, and increases in a stage-dependent manner, correlating with worsening patient survival." (PMID 38408962, 2024). "Specifically, FASN has been identified as the crucial enzyme for lipogenesis, and its increased expression has been linked with an unfavorable prognosis in various cancer types." (PMID 38933330, 2024).
cancer (continued). "Increased de novo fatty acid synthesis is an important hallmark of cancer cells, and fatty acid biosynthesis is catalyzed by multifunctional, homodimeric fatty acid synthase." (PMID 38195819, 2024). "Upregulation of FASN is associated with the progression of several cancers, including prostate, ovarian, breast, liver and cervical cancers." (PMID 39489738, 2024). "We then integrated CRISPR/Cas9-based knockout of the FASN gene with impedance-based cytotoxic assays to assess in real time assessment of how loss of FASN metabolic signaling alters cancer cell response to cytokine-activated T cells." (PMID 39349429, 2024). "Using CRISPR-based genetic loss-of-function approaches, we have shown that cancer cells are significantly more susceptible to cellular immune cytotoxicity when they are engineered to lack FASN gene and lipogenic function." (PMID 39349429, 2024). "Upregulated FASN expression has been reported to be associated with cell proliferation in multiple cancer types, including CRC." (PMID 38491348, 2024). "Several studies have implicated FASN in various cancers, highlighting its role in providing cancer cells with the necessary fatty acids for membrane synthesis, energy storage, and signaling pathways." (PMID 39071712, 2024). "FASN has garnered significant attention in cancer research due to its association with tumorigenesis and cancer progression." (PMID 39071712, 2024). "Fatty acid synthase (FASN) is an oncogene and is involved in cancer-associated metabolic reprogramming, and FASN-targeted drugs are in clinical development and trials." (PMID 38434684, 2024). "Here, we encountered that FASN expression negatively correlates with infiltrating immune cells associated with cancer suppression, cytolytic activity signatures, and HLA-I expression." (PMID 39349429, 2024). "Growth inhibition was observed in C75-treated FASN-overexpressing cancer cells compared with the response in FASN-deficient cancer cells." (PMID 39769395, 2024). "FASN encodes rate-limiting enzymes involved in fatty acid synthesis, which is a process essential for tumor growth and associated with the incidence of cancer-specific death." (PMID 38741777, 2024). "A multivariate regression analysis evaluated the association between FASN knockout (KO) and any other gene KO effect in >1,000 cancer cell lines." (PMID 39349429, 2024). "FASN expression negatively correlates with infiltrating immune cells associated with cancer suppression, cytolytic activity signatures, and HLA-I expression." (PMID 39349429, 2024). "To further investigate the predicted relationship between FASN expression and cancer immune evasion, we analyzed signatures associated with response or resistance to immunotherapy." (PMID 39349429, 2024). "Aberrant expression and activity of FASN is a hallmark of cancer development and progression in several tumor types, including human HCC." (PMID 39064589, 2024). "Cancer cells engineered to carry a loss-of-function mutation in FASN exhibit an enhanced cytolytic response and an accelerated extinction kinetics upon interaction with cytokine-activated T cells." (PMID 39349429, 2024). "FASN is associated with tumor invasiveness, and increased expression of FASN is positively correlated with lipid droplet formation and enhanced cancer cell activity." (PMID 38189049, 2023). "In contrast, high levels of FASN are observed in various malignancies, which have been linked to increased risks of cancer metastasis, recurrence, and poor survival." (PMID 37927468, 2023). "Suppressing FASN also caused a decrease in the hallmarks of tumors such as lipid production in various cancers such as pancreatic, ovarian, and lung tumors." (PMID 36677837, 2023). "The increase in fatty acid synthesis caused by the increased expression of FASN in cancer has been confirmed by a number of studies, and this process is closely linked to the malignant phenotype, poor prognosis and chemotherapy resistance of tumors." (PMID 36994237, 2023).
cancer (continued). "High expression of FASN, a critical regulator of lipid metabolism, is associated with cancer progression in various types of cancer in the breast, prostate, ovary, and liver." (PMID 38060103, 2023). "The upregulation of FASN in T-cell acute lymphoblastic leukemia (T-ALL) patient-derived cancer cells correlates with poor prognosis and drug susceptibility." (PMID 37256177, 2023). "Since upregulated ACC and FASN and deregulated protein palmitoylation are associated with many types of cancer, modulating FA synthesis pathway and protein palmitoylation have been considered as plausible anticancer strategies." (PMID 36617578, 2023). "FASN is a critical enzyme in de novo FA biosynthesis and its overexpression is associated with poor prognosis and chemotherapy resistance in cancer." (PMID 37444561, 2023). "FASN is commonly overexpressed in many epithelial and precancerous lesions and is associated with a high risk of cancer recurrence and mortality." (PMID 37700339, 2023). "FASN, the main lipase suppressed by orlistat, has been reported in association with the cell cycle progression of malignant tumors and the activation of signaling pathways, including the PI3K-AKT and the MEK/ERK pathways." (PMID 37283794, 2023). "FASN up-regulation and its association with a poor prognosis holds true for other cancer types as well, making this a universal cancer feature and thus supporting its usefulness as a therapeutic target of ccRCC." (PMID 36834678, 2023). "The elevated expression and activity of FASN in T-cell malignancies are linked with many other hallmarks of cancer." (PMID 37256177, 2023). "Regarding fatty acid synthase (FASN), increased expression is often reported in many different cancer types and has in fact been linked to gemcitabine resistance in KRAS mutated PDAC." (PMID 36675307, 2023). "There is increasing evidences of the involvement of FASN in several hallmarks of cancer linked to its ability to promote cell proliferation via membranes biosynthesis." (PMID 36934087, 2023). "FASN expression has been significantly associated with progression and outcome of several types of cancer such as colon, prostate, and soft tissue sarcomas." (PMID 35216362, 2022). "In EBV-driven cancer cell lines, inhibition of FASN was associated with a decrease in the BRLF1-mediated lytic viral genes, indicating that FA synthesis is required for EBV viral gene expression." (PMID 36497226, 2022). "Our results demonstrated that elevated FASN expression was significantly associated with an unfavorable prognosis in many cancer types." (PMID 36555243, 2022). "The complexity of citrate synthesis and utilization in cancer cells warrants the use of stable isotope tracing to better understand the metabolic adaptations associated with the downregulation of FASN expression in transgenic mouse models." (PMID 35742953, 2022). "Previous studies have reported that upregulated FASN levels in several cancers are associated with increased fatty acid synthesis and poor prognosis." (PMID 35216285, 2022). "Increased levels of FASN have been linked with decreased patient survival, increased disease recurrence, and increased invasive capacity of cancer in patients." (PMID 35634242, 2022). "Cancer cells show increased expression of genes encoding fatty acid synthase (FASN), which correlates with resistance to anticancer drugs targeting the epidermal growth factor receptor (EGFR)." (PMID 36569285, 2022). "MDA-MB-231 cells, whose FASN levels are low, can cover their lipid demand by using exogenous sources provided by cancer-associated fibroblasts in the microenvironment." (PMID 36010906, 2022). "Upregulated FASN expression has been reported to be associated with cancer progression in multiple cancer types, such as prostate cancer, ovarian cancer, breast cancer, and liver cancer." (PMID 35597782, 2022).
cancer (continued). "Recent research revealed that cholesterol was highly involved in cancer metastasis, and FASN was found to be linked with cholesterol metabolism." (PMID 35597782, 2022). "Aberrant FASN expression is implicated in several cancers, which is known to induce de novo lipogenesis and is involved in cell proliferation, survival, and invasion." (PMID 36028991, 2022). "Metabolic disorders had long been reported in EC, and over‐expression of fatty acid synthase is associated with cancer progression and upper body fat distribution in EC." (PMID 35778922, 2022). "Studies have found that FASN hyperactivity is common in human epithelial cell carcinoma or precancerous lesions, associated with a higher risk of cancer recurrence and death." (PMID 35743814, 2022). "As expected, targeting the emerging cancer hallmarks and PCa-specific vulnerability genes, such as FASN and HMGCR, AIF treatment caused the attenuation of PCa cell growth, migration, and invasion." (PMID 36362924, 2022). "Activation of SREBP-1c causes upregulation of FASN, enhances fatty acid metabolism, and theoretically promotes cancer development." (PMID 34539243, 2021). "The fatty acid synthase (FASN)‐encoded gene is highly expressed in several human cancers, highlighting the abnormal activation of de novo FA synthesis pathway." (PMID 34766135, 2021). "It seems that overexpression of both SCD1 and FASN is associated with increased production of TG, which include MUFAs that are conversely largely oxidized to provide energy to cancer cells." (PMID 34348720, 2021). "Cancer cells with upregulated PI3K signaling have been linked to increased FASN expression levels and enhanced glucose uptake thus fulfilling the increased need for membrane synthesis of rapidly dividing cells." (PMID 34907165, 2021). "Fatty acid synthase (FASN) is often overexpressed in human cancer and is associated with increased resistance to chemo- or radiotherapy." (PMID 33922595, 2021). "Overall, the findings revealed that FASN is dissimilarly associated with the outcome of cancer cases." (PMID 34879004, 2021). "Since the discovery in the mid-1990s of OA-519, an oncogenic antigen encoding for Fatty acid (FA) Synthase (FASN) highly expressed in breast cancer, research on the role of lipid metabolism in cancer has proceeded quite slowly with respect to other fields." (PMID 34386430, 2021). "In accordance with the discoveries in previous studies, FASN, an enzyme implicated in the process of metabolism, has shown to be positively correlated with the development of various cancers, including GC." (PMID 34456997, 2021). "As a result, USP14 overexpression reduced enzymatic activity of FASN, whereas USP14 deficiency significantly increased FASN activity in cancer cells." (PMID 34948233, 2021). "On the other hand, a number of cancer-associated reports shows that PI3K signaling modulates FASN levels as well in cancerous cells." (PMID 34642298, 2021). "Dysregulated FASN and lipogenesis is a hallmark of cancer, and cancer cells have been shown to become addicted to the FASN pathway and de novo lipogenesis." (PMID 33208446, 2021). "A favorable relationship was also found between FASN expression and cancer-associated fibroblasts in CESC, KIRC, KIRP, OV, and UVM." (PMID 34879004, 2021). "Cell death induced by FASNis is diminished by concurrent loss of pro-apoptotic proteins, suggesting that FASN activity regulates cancer cell survival by fine-tuning the mitochondrial threshold for apoptosis." (PMID 34675185, 2021). "Inhibition of p38 MAPK activity with SB203580 lessened the ability of C75 to upregulate BIM, NOXA, and PUMA, indicating that ROS-driven activation of stress-induced kinases is linked to the induction of BH3-only proteins in FASN-inhibited cancer cells." (PMID 34675185, 2021).